VPS4B (vacuolar protein sorting 4 homolog B)
Description:
Involved in late steps of the endosomal multivesicular bodies (MVB) pathway. Recognizes membrane-associated ESCRT-III assemblies and catalyzes their ATP-dependent disassembly, possibly in combination with membrane fission. Redistributes the ESCRT-III components to the cytoplasm for further rounds of MVB sorting. MVBs contain intraluminal vesicles (ILVs) that are generated by invagination and scission from the limiting membrane of the endosome and mostly are delivered to lysosomes enabling degradation of membrane proteins, such as stimulated growth factor receptors, lysosomal enzymes and lipids. VPS4A/B are required for the exosomal release of SDCBP, CD63 and syndecan. (Microbial infection) In conjunction with the ESCRT machinery also appears to function in topologically equivalent membrane fission events, such as the terminal stages of cytokinesis and enveloped virus budding (HIV-1 and other lentiviruses).
Synonyms: SKD1; MIG1; VPS4-2; SKD1B; DTDP1B
Tractability: Small molecule: a structure with a bound ligand is known; it has a binding pocket of medium quality. Antibody: UniProt places it where antibodies can reach, with high confidence. PROTAC: ubiquitination databases record sites on it; its protein half-life has been measured; a small molecule that binds it is known.
Target class: Enzyme; Hydrolase
Gene: Protein-coding gene on chromosome 18 (63,389,190 to 63,422,483, reverse strand). Ensembl gene ENSG00000119541.
Subcellular location: Late endosome membrane
Subcellular location (Human Protein Atlas): Vesicles
Pathways (Reactome):
Disease: Budding and maturation of HIV virion
Vesicle-mediated transport: Endosomal Sorting Complex Required For Transport (ESCRT)
Gene Ontology:
Molecular function: ATP hydrolysis activity; identical protein binding; protein binding; protein homodimerization activity; protein-containing complex binding; ATP binding
Biological process: endosomal transport; endosome to lysosome transport via multivesicular body sorting pathway; endosome transport via multivesicular body sorting pathway; ESCRT III complex disassembly; midbody abscission; mitotic metaphase chromosome alignment; negative regulation of exosomal secretion; nucleus organization; positive regulation of centriole elongation; positive regulation of exosomal secretion; positive regulation of G2/M transition of mitotic cell cycle; protein depolymerization; regulation of centrosome duplication; regulation of mitotic spindle assembly; response to lipid; viral budding from plasma membrane; viral budding via host ESCRT complex; autophagosome maturation; autophagy; late endosome to lysosome transport via multivesicular body sorting pathway; macroautophagy; membrane fission; multivesicular body assembly; multivesicular body sorting pathway; nuclear membrane reassembly; and 5 more
Cellular component: centrosome; cytoplasm; endosome; endosome membrane; extracellular exosome; Flemming body; nucleus; spindle pole; ATPase complex; cytosol; late endosome membrane; midbody; nuclear pore; plasma membrane
Genetic constraint (gnomAD): Loss-of-function variants: 18 observed, 48.67 expected, observed/expected ratio (o/e) 0.37, 90% interval 0.25 to 0.55. The upper end of that interval is the gene's LOEUF score, 0.55, which puts it in group 2 of 6, group 1 being the genes least tolerant of losing a copy. Missense variants: 341 observed, 507.35 expected, observed/expected ratio (o/e) 0.67, 90% interval 0.61 to 0.74. Synonymous variants: 169 observed, 178.01 expected, observed/expected ratio (o/e) 0.95, 90% interval 0.84 to 1.08.
Homologues: Orthologues: macaque VPS4B (99% identical), chimpanzee VPS4B (98% identical), mouse Vps4b (95% identical), guinea pig VPS4B (95% identical), rat Vps4b (95% identical), pig VPS4B (95% identical), rabbit VPS4B (95% identical), dog VPS4B (95% identical), tropical clawed frog vps4b (88% identical), zebrafish vps4b (86% identical), Drosophila melanogaster Vps4 (75% identical), Caenorhabditis elegans vps-4 (68% identical), and 1 more. Paralogues in human: VPS4A (80% identical), SPAST (36% identical), KATNA1 (35% identical), KATNAL1 (35% identical), FIGNL1 (34% identical), KATNAL2 (34% identical), FIGN (28% identical), ATAD1 (26% identical), FIGNL2 (23% identical).
Diseases named in the same sentence as VPS4B in open-access papers:
VPS4B is named in the same sentence as 36 diseases in open-access papers, as found by Europe PMC text mining. Sharing a sentence is not in itself a finding about the gene and the disease. The quoted sentences say what the papers report.
breast carcinoma (6 papers, 2013 to 2023). "Toward gaining a more thorough understanding of the consequences of altered EGFR signaling caused by VPS4B dysfunction, we developed an iSDMS method to identify changes in the protein synthesis, degradation rates, and dynamic protein expression, in breast cancer SKBR3_shVPS4B cells." (PMID 23431444, 2013). "Most importantly, we have also identified many previously unidentified energy metabolism pathways that were altered as a result of VPS4B downregulation in breast cancer." (PMID 23431444, 2013). "Currently, we are in the process of identifying what protein cargos are specifically targeted and degraded by the Vps4B-dependent MVB-lysosomal degradation system in breast cancer." (PMID 23431444, 2013). "To further understand the role of VPS4B dysfunction in breast cancer, we set out to determine the consequences of altered EGFR signaling: changes in protein synthesis and degradation, as well as protein dynamics in VPS4B downregulated breast cancer cells." (PMID 23431444, 2013). "As downregulation of VPS4B has been reported to be associated with certain high grade and recurring tumors, the adoption of fatty acid β-oxidation as an alternative energy source could be a distinct feature of breast cancer cells with VPS4B dysfunction." (PMID 23431444, 2013). "The adoption of fatty acid β-oxidation as an alternative energy source could be an unrevealed survival mechanism for breast cancer cells with VPS4B dysfunction." (PMID 23431444, 2013). "Recently, we have shown that dysfunction and down-regulation of vacuolar protein sorting 4B (VPS4B), an ESCRT-III associated protein, under hypoxic conditions can lead to the abnormal accumulation of epidermal growth factor receptor (EGFR) and aberrant EGFR signaling in breast cancer." (PMID 23431444, 2013). "Identification of specific cargos that are delayed by VPS4B-dependent target degradation is likely going to provide critical information on whether these proteins can be used as potential biomarkers for both the classification and progression of breast cancer." (PMID 23431444, 2013). "Taken together with our preliminary data that indicate a role for VPS4B in exosome production, we hypothesize that there is a mechanistic link between hypoxia, MVB function, exosome production and radiation resistance in breast cancer." (PMID 24860738, 2013). "Nevertheless, we cannot exclude that VPS4B downregulation may be beneficial for cells of advanced‐stage CRC, as RNAi‐mediated knockdown of VPS4B may promote resistance of multiple melanoma and breast cancer cells to chemotherapeutics." (PMID 31930723, 2020).
pancreatic cancer (3 papers, 2022 to 2023). "Transplantation of VPS4B-deficient pancreatic tumors into immune competent mice impairs autophagy and resulting in increased accumulation of CD8 T cell-derived granzyme B and tumor cell lysis." (PMID 37404768, 2023). "Orthotopic transplantation of Vps4b- or Rnf31 deficient pancreatic tumors into immune competent mice, moreover, reveals increased CD8+ T cell infiltration and effector function, and markedly reduced tumor growth." (PMID 35379808, 2022). "VPS4B is also positively associated with pancreatic cancer development." (PMID 37404768, 2023). "Notably, both MYO5B and VPS4B within the rearrangement region were upregulated in pancreatic cancer and associated with poor prognosis." (PMID 35570408, 2022). "Here, based on in vitro and in vivo CRISPR screens, the authors identify Rnf31 and Vps4b as drivers of immune escape, showing that loss of their function leads to an increase in T cell-mediated killing and reduced tumor growth in preclinical pancreatic cancer models." (PMID 35379808, 2022).
breast tumors (2 papers, 2023 to 2024). "There is a negative correlation between VPS4B expression and EGFR stability in breast tumors." (PMID 37404768, 2023).
colorectal cancer (2 papers, 2020 to 2025). A primary or metastatic malignant neoplasm that affects the colon or rectum. "Here, we showed that the VPS4B gene was frequently deleted in many cancer types, including in colorectal cancer, which was reflected by low VPS4B mRNA and protein levels in colorectal cancer samples from patients." (PMID 31930723, 2020). "Here, we report that VPS4B gene, encoding an ATPase involved in ESCRT‐dependent membrane remodeling, is such a passenger gene frequently deleted in many cancer types, notably in colorectal cancer (CRC)." (PMID 31930723, 2020).
hepatocellular carcinoma (2 papers, 2020 to 2023). A malignant tumor that arises from hepatocytes. "On the other hand, high expression of VPS4B is associated with faster cell proliferation and poor prognosis in hepatocellular carcinoma." (PMID 36979661, 2023). "Changes in mRNA or protein abundance of VPS4A or VPS4B were reported in hepatoma, breast, and non‐small‐cell lung cancer." (PMID 31930723, 2020).
adenoma (1 paper, 2020). A neoplasm arising from the epithelium. "Using qRT–PCR analysis, we confirmed significantly downregulated VPS4B expression, which indicated that its mRNA levels decreased during progression from adenoma to adenocarcinoma." (PMID 31930723, 2020). "Accordingly, we discovered that VPS4B expression is progressively downregulated from adenoma to adenocarcinoma and confirmed a decreased abundance of VPS4B protein in treatment‐naïve primary CRC samples." (PMID 31930723, 2020).
adrenocortical cancer (1 paper, 2023). "Finally, Vacuolar protein sorting-associated protein 4B (VPS4B) was found to be downregulated in rectum adenocarcinoma, colon adenocarcinoma, ovarian serous cystadenocarcinoma, adrenocortical cancer and testicular germ cell tumor." (PMID 36979661, 2023).
colon carcinoma (1 paper, 2020). "In these experiments, we used CT‐26 cells, a mouse colon carcinoma line that was transiently transfected by siRNA targeting mouse Vps4a and Vps4b (Fig EV5A and B)." (PMID 31930723, 2020). "First, we confirmed that silencing of Vps4a and Vps4b in mouse colon cancer cells recapitulated the synthetic lethality observed in human CRC cells, such that it was accompanied by activation of caspase 7 and canonical NF‐κB signaling leading to cell death (Fig EV5B and C)." (PMID 31930723, 2020).
congenital dyserythropoietic anemia (1 paper, 2024). Congenital dyserythropoietic anemia (CDA) is a heterogenous group of hematological disorders of late erythropoiesis and red cell abnormalities that lead to anemia. "First, mutations in VPS4A in patients carrying normal VPS4B caused severe diseases associated with structural brain abnormalities, neurodevelopmental defects, cataract, growth defects, and congenital dyserythropoietic anemia (CDA)." (PMID 38687820, 2024).
Crohn disease (1 paper, 2023). A gastrointestinal disorder characterized by chronic inflammation involving all layers of the intestinal wall, noncaseating granulomas affecting the intestinal wall and regional lymph nodes, and transmural fibrosis. "Moreover, VPS4B regulates apoptosis of chondrocytes via p38 Mitogen-Activated Protein Kinases (MAPK) in osteoarthritis and Crohn’s disease, providing a possible pathway by which VPS4 series proteins affect tumors." (PMID 37404768, 2023).
dentin dysplasia type I (1 paper, 2020). Dentin dysplasia type I (DD-I) is a rare form of dentin dysplasia (DD) characterized by sharp conical short roots or rootless teeth. "A splicing mutation in VPS4B can cause dentin dysplasia type I (DD-I), a hereditary autosomal-dominant disorder characterized by rootless teeth, the etiology of which is genetically heterogeneous." (PMID 32737282, 2020).
familial Alzheimer disease (1 paper, 2017). A degenerative disease of the brain that causes gradual loss of memory, judgment, and the ability to function socially. "While the ESCRT-III protein CHMP2B was first genetically linked to FTD, copy number variation in CHMP2B has since been reported in a family with familial Alzheimer’s disease and genome-wide association studies for late onset AD identified an association with VPS4B." (PMID 28835279, 2017).
Flavivirus Infections (1 paper, 2023). Infections with viruses of the genus FLAVIVIRUS, family FLAVIVIRIDAE. "A plausible reason for this finding could be a functional redundancy between VPS4A and VPS4B that would compensate for the lack of VPS4A at particular infection stages, as has previously been described for other ESCRT components such as CHMP2 or CHMP4 families in flavivirus infection." (PMID 38125905, 2023).
frontotemporal dementia (1 paper, 2017). Frontotemporal dementia (FTD) comprises a group of neurodegenerative disorders, characterized by progressive changes in behavior, executive dysfunction and language impairment, as a result of degeneration of the medial prefrontal and frontoinsular cortices. "CHMP2B, linked genetically to frontotemporal dementia (FTD) and AD, directly interacts with and recruits the VPS4 AAA–ATPase complex that disassembles ESCRT-III, and genome-wide association studies for late onset AD identified an association with VPS4B." (PMID 28835279, 2017).
glioma (1 paper, 2015). A benign or malignant brain and spinal cord tumor that arises from glial cells (astrocytes, oligodendrocytes, ependymal cells). "VPS4B, VAMPs and CHMPs are components of the ESCRT-III, which suggests that the major mechanism of MDR in glioma is exocytosis." (PMID 25333456, 2015).
Insulin resistance (1 paper, 2021). Increased resistance towards insulin, that is, diminished effectiveness of insulin in reducing blood glucose levels. "Interestingly, LUZP6 RNA is enriched in salivary exosomes and, together with another three genes (IL1R2, VPS4B and CAP1) comprising an RNA signature, could distinguish high from low insulin resistance as an extracellular RNA marker." (PMID 34073722, 2021).
viral infection (1 paper, 2017). "We were next interested in determining whether we could detect interaction between endogenous VPS4B and the components of the viral capsid during a viral infection." (PMID 28349933, 2017).
tumor (17 papers, 2013 to 2026). "Loss of Vps4b in cancer cells impairs autophagy, leading to increased accumulation of Granzyme B intracellular, and thus enhances the sensitivity of tumor cell to CD8+ T cell effector function." (PMID 37427373, 2023). "Using an orthotopic transplantation model, we further demonstrate that loss of Rnf31 and Vps4b gene function leads to reduced tumor growth and increasing T cell infiltration and effector function in vivo." (PMID 35379808, 2022). "They found that VPS4A is essential in cancers with VPS4B loss adjacent to SMAD4 on chromosome 18q, and VPS4B is required in tumours with co‐deletion of VPS4A and CDH1 (E‐cadherin) on chromosome 16q." (PMID 34254730, 2021). "Using this approach, we demonstrated that the induction of shVPS4A expression in xenografted HCT116 VPS4B−/− cells caused a significant retardation in tumor growth." (PMID 31930723, 2020). "In summary, high expression of VPS4B is associated with tumor proliferation and poor prognosis, suggesting that VPS4B may become an important assessment factor in tumor staging." (PMID 37404768, 2023). "They performed in vivo functional validation of this synthetic lethal relationship by inducing CRISPR‐SpCas9‐mediated VPS4A suppression in rhabdomyosarcoma and pancreatic ductal adenocarcinoma PDTXs deficient of VPS4B and showed this resulted in near‐complete tumour regression." (PMID 34254730, 2021). "Although the molecular mechanisms underlying the hypoxia-induced VPS4B-associated tumor angiogenesis and metastasis remain unknown, our results clearly indicate that there is a direct link between altered lipid metabolism and VPS4B-mediated MVB dysfunction." (PMID 23431444, 2013). "Tumor cells often lose one VPS4 paralog (VPS4A or VPS4B), making them dependent on the remaining enzyme and creating a potential therapeutic vulnerability." (PMID 42032367, 2026). "al found that in immunocompromised NU/J mice, injection of HCT116 cells with the knockout of VPS4B and doxycycline (Dox)‐inducible VPS4A‐targeting shRNA expression (HCT116 VPS4B −/− shVPS4A) inhibits tumor growth in mouse." (PMID 37404768, 2023). "The results showed that the expression levels of PYGB, IFNGR2, TICAM1, STAT6 and VPS4B in CHOL tissues showed an overall upward trend compared with non-tumor hepatobiliary duct tissues." (PMID 36936916, 2023). "In tumor cells, knockout of Vps4b led to an increased expression of Vps4a to compensate for these functions." (PMID 37445978, 2023). "Our prognostic signature consists of five genes, PYGB, IFNGR2, TICAM1, STAT6, and VPS4B, each of which plays a critical role in necroptosis and tumor progression." (PMID 36936916, 2023). "VPS4B codes for a protein that is involved in autophagy that can reduce the sensitivity of T cell-mediated tumor cell lysis by lowering granzyme B content, and it is an essential factor required for escaping CD8+ T cell-mediated killing in tumors." (PMID 36936916, 2023). "In NSCLC, VPS4B showed high expression and a significant correlation with tumor size, histological differentiation, clinical stage, and Ki-67." (PMID 37404768, 2023). "To systematically explore which of these effector mechanisms are sensitized upon Rnf31 and Vps4b inhibition, we first assessed tumor cell sensitivity to TNF ligands." (PMID 35379808, 2022). "Analysis of two of the strongest hits, Vps4b, and Rnf31, demonstrated that their inhibition sensitizes tumor cell clearance directly, via cell-autonomous mechanisms, and indirectly, by increasing the number and functionality of intratumoral CD8+ T cells." (PMID 35379808, 2022). "As the tumor stroma is known to be an important determinant for PDA prognosis and treatment, addressing the effect of Rnf31 and Vps4b depletion in the context of the tumor stroma would be highly valuable." (PMID 35379808, 2022).